HSPA9 (heat shock protein family A (Hsp70) member 9)
Diseases named in the same sentence as HSPA9 in open-access papers (continued):
Sharing a sentence is not in itself a finding about the gene and the disease.
cryptorchidism (1 paper, 2020). The failure of one or both testes of a male fetus to descend from the abdomen into the scrotum during the late part of pregnancy. "For example, the ovarian failure in Perrault syndrome and the genital abnormalities (e.g., cryptorchidism/hypospadia) associated with variants in HSPA9 and DNAJC19 could be due to altered levels of sex hormones." (PMID 33171986, 2020).
depression (1 paper, 2024). "We employed conditioned microglia-specific Hspa9 knockout mice (Cx3cr1CreER/+/Hspa9f/+) to confirm whether GRP75 (Hspa9) is involved in CSDS-induced depression-like behaviors." (PMID 38890305, 2024).
diabetic nephropathy (1 paper, 2024). "In renal fibrosis caused by diabetic nephropathy, lncRNA ENSMUST00000147869 directly binds to the heat shock protein HSPA9, reduces its expression through ubiquitination degradation, and inhibits the interaction between HSPA9 and HMGB1, thereby inhibiting the development of renal fibrosis." (PMID 39113708, 2024).
dysferlinopathy (1 paper, 2023). "Further studies are required to verify the role of HSPA9 and the mTORC1 pathway in the pathomechanism of dysferlinopathy." (PMID 38125829, 2023). "Analysis of muscle transcripts from patients with dysferlinopathy helped identify the following 7 upregulated DEGs involved in the cellular response to stress: HSPA9, RPTOR, MTOR, LAMTOR1, LAMTOR5, ATP6V0D1, and ATP6V0B." (PMID 38125829, 2023). "HSPA9 has varying functions depending on the cell type and interacting proteins; therefore, further research is required to clarify the significance of intramuscular HSPA9 expression in dysferlinopathy." (PMID 38125829, 2023). "In dysferlinopathy, overexpression of HSPA9 and the mTORC1 signaling pathway genes was detected." (PMID 38125829, 2023).
glioma (1 paper, 2013). A benign or malignant brain and spinal cord tumor that arises from glial cells (astrocytes, oligodendrocytes, ependymal cells). "For example, HSPA9 is not only upregulated in a variety of cancers, but its expression also correlates with glioma grade and the proliferative potential of cells." (PMID 24068912, 2013).
microtia (1 paper, 2024). "Nevertheless, TCOF1 and HOXA2, in turn, cause microtia in a dominant manner, suggesting haploinsufficiency, while HSPA9 and GSC are in recessive mode of inheritance." (PMID 38594752, 2024). "In the syndromic microtia group, the most common genes were TCOF1 (43.75%), SIX2 (4.69%), and HSPA9 (4.69%), while in the non-syndromic microtia group, the most frequently found gene was GSC exon 2 (25%), FANCB (16.67%), HOXA2 (8.33%), GSC exon 3 (8.33%), MARS1 (8.33%), and CDT1 (8.33%)." (PMID 38594752, 2024). "Based on our findings, 64 cases (72.72%) were syndromic microtia [TCOF1 (43.75%), SIX2 (4.69%), and HSPA9 (4.69%)] and 24 cases (27.27%) were non-syndromic microtia [GSC exon 2 (25%), FANCB (16.67%), HOXA2 (8.33%), GSC exon 3 (8.33%), MARS1 (8.33%), CDT1 (8.33%)]." (PMID 38594752, 2024). "As reported in this review, the major gene disorder related to microtia phenotype is found in TCOF1 (32.82%; 28 cases), followed by GSC exon 2 (6.82%), FANCB (4.55%), SIX2 (3.41%), HSPA9 (3.41%) and CDT1 (3.41%) with each characteristic." (PMID 38594752, 2024). "In the syndromic microtia group, the most common genes were TCOF1 (43.75%; 28 out of 64 cases), SIX2 (4.69%), and HSPA9 in (4.69%) patients." (PMID 38594752, 2024). "We found 88 cases of genetic data related to microtia, including TCOF1 (31.82%), GSC exon 2 (6.82%), FANCB (4.55%), SIX2 (3.41%), HSPA9 (3.41%), and CDT1 (3.41%)." (PMID 38594752, 2024). "In addition, HSPA9, MARS1, and TCOF1 were the only genes related to familial microtia." (PMID 38594752, 2024).
Sepsis (1 paper, 2025). Sepsis is defined as life-threatening organ dysfunction caused by a dysregulated host response to infection. "In the present study, we found that the expression of HSPA8 and HSPA9 was significantly reduced in the serum of patients with sepsis-induced ALI compared to healthy individuals." (PMID 40694561, 2025). "In conclusion, VDAC1, HSPA8, SOD1, HSPA9, TXN, and SNCA have been identified as oxidative stress-related genes associated with sepsis-induced ALI." (PMID 40694561, 2025). "The expression levels of VDAC1, HSPA8, SOD1, and HSPA9 were significantly decreased in the sepsis-induced ALI group compared to the control group (p < 0.0.5)." (PMID 40694561, 2025). "Our findings revealed that both the mRNA expression levels and protein concentrations of HSPA8 and HSPA9 were significantly reduced in the blood samples of patients suffering from sepsis-induced ALI." (PMID 40694561, 2025). "Therefore, we next analyzed the expression of VDAC1, HSPA8 and HSPA9 in the blood samples of patients with sepsis-induced ALI at the clinical level." (PMID 40694561, 2025). "The proportion of neutrophils exhibited a significant negative correlation with the expression of VDAC1, HSPA8, SOD1, HSPA9 and TXN, and a significant positive correlation with SNCA expression in sepsis-induced ALI." (PMID 40694561, 2025). "The logistic regression algorithm identified 8 genes (VDAC1, HSPA8, SOD1, HSPA9, TXN, NDUFS3, HSP90AB1, SNCA), among which 6 genes were closely correlated with the onset of sepsis-induced ALI (p < 0.05)." (PMID 40694561, 2025). "Finally, we analyzed the expression of VDAC1, HSPA8, SOD1, HSPA9, TXN, and SNCA in sepsis-induced ALI in the meta-GEO cohort." (PMID 40694561, 2025).
somatotropinomas (1 paper, 2018). "In addition, upregulation of NME1 (2.16-fold change, P = 0.03) and HSPA9 (2.37-fold change, P = 0.05) was observed in AIPmut positive somatotropinomas, compared with normal pituitary." (PMID 29507682, 2018).
cancer (92 papers, 2007 to 2025). A tumor composed of atypical neoplastic, often pleomorphic cells that invade other tissues. "Recent literature has demonstrated that HSPA9 expression is upregulated and associated with poor prognosis in many types of cancer patients." (PMID 39261452, 2024). "The interaction between MMP3 and HSPA9 can impact cancer therapy by influencing ER-mitochondrial calcium flux, cell fate under stress, and mitochondrial function." (PMID 40362252, 2025). "Of these, HSPA8, HSPA9, PKM, HNRNPA1, NPM1, ANXA2 are already reported to be associated with LN metastasis in GBC or other cancers." (PMID 37142981, 2023). "miPEP133 promotes anti-cancer effects by interacting with HSPA9 in the mitochondria where it inhibits interactions between HSPA9 and its binding partners." (PMID 37213226, 2023). "Mortalin (mtHsp70/GRP75/PBP74/HSPA9/HSPA9B) promotes cancer development, progression, metastasis, and recurrence." (PMID 36899836, 2023). "The downregulation of EGLN2 and HSPA9 enables cancer cell proliferation even under low oxygen conditions." (PMID 38117844, 2023). "Using human serous OC scRNA-seq data, GSEA demonstrated enrichment of several cancer-related gene pathways in OC with high mortalin (HSPA9) expression." (PMID 36899836, 2023). "Among these proteins, we found a more interesting protein, HSPA9, which was related to proliferation, function maintenance and stress response in cancer cells." (PMID 33191617, 2021). "HspA4 (a non-canonical Hsp70 member), HspA5 (an Hsp of the endoplasmic reticulum (ER) also referred to as Grp78), and HspA9 (a mitochondrial Hsp also referred to as Grp75) have been demonstrated to activate Akt in cancer models." (PMID 34222357, 2021). "More recently, the downregulation of heat shock protein family A member 9 (HSPA9) was reported to induce pexophagy in cancer cells." (PMID 32674458, 2020). "In the HSP70 family, HSPB12B positively correlated with 25 cancer types, while HSPA9 negatively correlated with 11 cancer types." (PMID 33225964, 2020). "Among HSP70 family, five members have been especially well examined in association with cancer, which are stress-inducible HSP70s, HSP72 (HSPA1) and HSP70B (HSPA6), and constitutively expressed HSP70s, HSC70 (HSPA8), GRP75/Mortalin (HSPA9), and GRP78 (HSPA5)." (PMID 31878360, 2019). "Suppression of the gene HSPA9 expression or interference with interaction would be a therapeutic strategy against cancer." (PMID 31534628, 2019). "Recently, many studies have confirmed that HSPA9 promotes the occurrence and progression of cancer by promoting tumor cell proliferation, inhibiting tumor cell apoptosis, and promoting angiogenesis." (PMID 31379979, 2019). "In other settings, HSPA9 exhibits oncogenic properties, making it a potential therapeutic target for cancer." (PMID 29507682, 2018). "HSPA9/mortalinis also abundantly present in the surface of cancer cells, including SH-SY5Y cells.Studies to elucidate its interaction with TLQP-21 are therefore warranted; in particular, to confirm if TLQP-21 binds to a cell surface fraction of HSPA9." (PMID 28934328, 2017). "This is the reason why mitochondrial hsp70 (HSPA9) has been widely observed in cancer drug-resistance researches 31 as well as in aggressive cancer studies." (PMID 25639359, 2015). "In comparison with normal cells, most cancer cells overexpress mitochondrial hsp70 (HSPA9) at the basal level to resist to various damages at different stages of tumourigenesis and during anti-cancer treatment." (PMID 25639359, 2015). "Furthermore, Takeda-G-protein receptor-5 (TGR5) accelerates cancer cell proliferation and migration and promotes cell death resistance partially by interacting with HSPA9." (PMID 39261452, 2024).
cancer (continued). "Interestingly, HSPA9 is regarded as a proto-oncogene and is aberrantly overexpressed in several cancer types." (PMID 39113711, 2024). "Additionally, several analogs of MKT-077, such as JG-98, JG-194 and JG-231, have been synthesized to bind to HSPA9 and suppress cancer cell growth, thereby enhancing the clinical translational value of MKT-077." (PMID 39261452, 2024). "In addition, the inhibition of HSPA9 has been shown to induce mitochondrial stress and cancer cell death." (PMID 37170364, 2023). "Indeed, knockdown of the gene HSPA9 by ribozyme or siRNA was shown to reduce growth and viability of human cancer cells and to decrease exosome release." (PMID 33833900, 2019). "Therefore, suppression of the gene HSPA9 expression or interference with interaction would be a likely therapeutic strategy against cancer." (PMID 33833900, 2019). "Also, numerous studies link TXNDC5’s high expression with cancer, and there may be a possible connection between that and HSPA9." (PMID 38138960, 2023). "We tested the effect of CB6644 (targeting RUVBL1/2 complex), MKT077 (inhibiting HSPA9), selinexor (blocking XPO1, nuclear exportin), and MeAIB (targeting SLC38A2) on cell lines representing three different cancer types versus the normal fibroblasts." (PMID 39217152, 2024). "Proteomic analysis identifies adenine nucleotide translocase 3 (ANT3) as an interacting protein of HSPA9 and indicates that HSPA9 can disrupt the interaction between ANT3 and cyclophilin D (CypD) in BRAF mutant cancer cells." (PMID 39261452, 2024). "Alterations in the levels of some proteins in the COS–GA group, such as HSPA9, HIST2H2BF, keratin 18, HINT1, and vimentin, were proposed as anti-cancer mechanisms in this study." (PMID 37371778, 2023). "Anti-cancer-activity-related proteins were altered, including CLTA, HSPA9, HIST2H2BF, KRT18, HINT1, DSP, and VIM." (PMID 37371778, 2023). "Other studies showed that HSPA9 and HSPA4 influence the biological behavior of tumor cells to promote cancer progression." (PMID 34712697, 2021). "For example, knockout of HSPE1, HSPA9, and DNAJC9 significantly reduced cell proliferation across 21 cancer cell lineages." (PMID 33225964, 2020). "For DCIS tissues, compared with both DCIS cancer-adjacent and normal tissues, we detected four up-regulated (GAPDH, HSPA9, CCT4, and SCPEP1) and 48 down-regulated proteins (including KRT10, APOA1, ALDH1A1, and others) in DCIS tissues." (PMID 33194682, 2020). "This phenomenon has been observed in vitro in multiple cancer cell lines, including NIH/3T3, A-172, U-2 OS, and HeLa, where its interaction with HspA9 prevents nuclear translocation, thereby inhibiting its transcriptional activity and promoting its degradation via the proteasome." (PMID 40214463, 2025). "Thus, knockdown of HSPA9 markedly suppresses cell proliferation, inhibits EMT, induces cell cycle arrest and initiates cell death in various cancer cells." (PMID 39261452, 2024). "Moreover, HSPA9 blocks the degradation of high mobility group A1 (HMGA1) and promotes the activation of the HMGA1/JNK/c-Jun axis in lung cancer to stimulate cancer cell growth and metastasis." (PMID 39261452, 2024). "Using RNAi screening of the commonly activated molecular programs, we found a signature of three proteins - RUVBL1, HSPA9, and XPO1, which could be efficiently targeted by novel drug combinations in the studied cancer types." (PMID 39217152, 2024).
cancer (continued). "HSPA9 not only modulates the Raf/MEK/ERK signaling pathway but also promotes the PP1α-MER1/2 interaction to increase MEK1/2 dephosphorylation in KRAS and BRAF mutant cancer cells." (PMID 39261452, 2024). "However, six proteins influenced cancer cell survival in the COS–GA group in previous studies, with downregulated HSPA9 and HIST2H2BF and upregulated KRT18, HINT1, DSP, and VIM proteins." (PMID 37371778, 2023). "Additionally, ESCC biomarkers identified in previous study, such as ACTA2, ANXA1, HSPA9, THBS1 etc. were also detected in EESCC, indicating the key events in advanced-stage cancer happened as earlier as in the early-stage cancer." (PMID 35397555, 2022). "Low levels of HSP90AB1/TRAP1, HSPA6/TRAP1, and HSP90AA1/TRAP1 in urine increase the probability of the patient having cancer, whereas low levels of CCT2/HSP90AB1 and HSPB1*HSPA9 in urine are strongly associated with non-cancer groups." (PMID 34692733, 2021). "CCT1, CCT5, and FKBP4 showed significantly lower expression in the cancer patients compared to the healthy volunteers, whereas HSPA9 and TRAP1 showed a significantly higher expression in patients with cancer compared to the control group for the most cancer types." (PMID 34692733, 2021). "Indeed, knockdown of the gene HSPA9 by ribozyme or small interference RNA (siRNA), including treat with MKT-077 reduces cell growth and viability of human cancer cells." (PMID 31534628, 2019). "This mandates a search for targetable signatures, such as RUVBL1, HSPA9, and XPO1, whose redundancy is limited by directly non-overlapping roles in cancer cell metabolism." (PMID 39217152, 2024). "These HSP70-specific inhibitors may not distinguish HSPA9 from HSPA12B, which may lead to complicated consequences in anti-cancer therapy." (PMID 33225964, 2020).
tumor (68 papers, 2008 to 2025). "In line with previous studies, the HSPA9 indicator was mainly observed in tumor cells, while HSPA9 was predominantly associated with malignant cells." (PMID 38312844, 2024). "HSPA9 encodes a member of the heat shock protein 70 gene family, highly expressed in tumor cells and tissues, and it plays a role in extending cell life, mitochondrial capacity, chaperones, transformation of oncogenes, low differentiation of tumor cells, and stress reactions." (PMID 33681194, 2021). "MKT-077 is an inhibitor obtained from rhodacyanine dye that impacts the interaction of nucleotide exchange factors (NEFs) with HSPA8 and HSPA9, inhibiting tumor growth and inducing cell senescence." (PMID 41369386, 2025). "Immunoblots confirmed the high levels of 75-kDa glucose regulatory protein (GRP75), encoded by Hspa9, and UCP1 proteins in the iWAT of YES2 tumour-bearing mice from T-1 to T-3." (PMID 39327432, 2024). "HSPA9 was reported to maintain MEK-ERK-driven tumor cell survival through inhibiting ANT3-mediated mitochondrial membrane permeability." (PMID 39113711, 2024). "Using human serous OC scRNA-seq data, we showed higher expression of HSPA9 in tumor cells compared to tumor-infiltrating immune cells (i.e., myeloid cells and T cells)." (PMID 36899836, 2023). "GRP75 (known as mortalin or HSPA9) has its main location in the mitochondria and exhibits antiapoptotic potential; this chaperone is thought to be one of the factors defining tumor growth/resistance to therapeutics." (PMID 33806538, 2021). "HSPA9 is involved in tumor processes and in heparan sulfate proteoglycan (HSPG)-mediated endocytosis." (PMID 32760390, 2020). "Mortalin or HSPA9, the mitochondria-resident HSP70 isoform, has been also implicated in ovarian carcinogenesis and tumor malignancy." (PMID 31540420, 2019). "EMSA assays also revealed weak DNA binding activity at one of the several c-Myc binding sites in the Hspa9 promoter sites and this protein functions as a master regulator for tumor specific up-regulated genes." (PMID 26427040, 2015). "However, by inducing the translocation of mitochondrial HSPA9 to the nucleus, MUL1-induced SUMOylation of HSPA9 played a tumor suppressive role in BCa cells." (PMID 39113711, 2024). "The N-terminus and C-terminus of HSPA9 interact with HSP90B1 to regulate tumor cell functions." (PMID 34712697, 2021). "The overexpression of HSPA9 in normal cells could effectively prolong cell life, while the inhibition of HSPA9 expression in tumor cells could lead to senescence or apoptosis of tumor cells." (PMID 32041309, 2020). "HSPA9 has been proved to be a candidate tumour suppressor gene." (PMID 26569224, 2015). "Excess dietary iron in tumor tissues was also associated with significant changes (generally, increases; p ≤ 0.05) in proteins involved in modulating cell protein integrity (HSPA5, HSPA9, ITGB1, PSMA4, DPP7, and PEPD), cell mobility and growth (CAPZB), and immunologic factors (FCGBP)." (PMID 38732562, 2024). "In the analysis of DEGs, we focused on the genes HSPA9 and HSPD1, which influence tumor cell survival by regulating the stability of the mitochondrial membrane and the conformation and thus function of mitochondrial proteins." (PMID 40362672, 2025). "In view of our findings indicating the activation of STAT3 signaling pathway through the degradation of SUZ12 and EZH2 mediated by SUMOylated HSPA9, we investigated the role of STAT3 in MUL1-induced tumor inhibition effects." (PMID 39113711, 2024). "The results showed the expression of tumor malignant characteristic genes such as CDKN2A CKS1B, HSPA9, IDH2, and MYC among different subpopulations of plasma cells, with high expression in plasma cell_2." (PMID 39271659, 2024). "Antibody 15-7, which was derived from a single PC clone in the tumor from patient 15, costained with antibodies specific for the mitochondrial markers, COX4I1 and HSPA9." (PMID 37751306, 2023).